PLK1 (polo like kinase 1)
Diseases named in the same sentence as PLK1 in open-access papers (continued):
Sharing a sentence is not in itself a finding about the gene and the disease.
breast invasive carcinoma (9 papers, 2009 to 2024). "In particular, a statistically significant association was found between CHEK1, MAP2K1, and PLK1 overexpression and worse overall survival in breast invasive carcinoma patients, indicated by pooled hazard ratio (HR) values higher than 1 and p-values lower than 0.05." (PMID 33898418, 2021). "The results of the boxplot analysis indicated overexpression of CHEK1 and PLK1 in breast invasive carcinoma compared to healthy controls, aligning with our findings." (PMID 39473450, 2024). "Using IHC, PLK1 was detected at a high level in invasive carcinomas of the breast and undetected in normal breast tissue." (PMID 19619298, 2009). "Notably, protein–protein interaction (PPI) network analysis identified CHEK1 and PLK1 as central hub genes with overexpression correlating with poor prognosis in invasive breast carcinoma." (PMID 39473450, 2024). "To investigate the clinical significance of the upstream (PLK1) and downstream (CDK1) modulators of FOXC2, we analyzed the data from a cohort of patients with invasive breast cancers following taxane-anthracycline chemotherapy." (PMID 27064522, 2016). "Moreover, the significance of this observation is reiterated by our finding that PLK1 and the FOXC2 potential target CDK1 mRNA collectively predict poor DRFS among invasive breast cancer patients after taxane-anthracycline chemotherapy." (PMID 27064522, 2016).
neutropenia (9 papers, 2011 to 2025). A decrease in the number of neutrophils found in the blood. "The AEs associated with Plk1 inhibitors were mainly hematological, namely, neutropenia and thrombocytopenia, but the safety profile of most molecules was considered acceptable and manageable." (PMID 34371703, 2021). "However, while PLK-1 inhibitors block tumor growth, they have been shown to cause severe adverse complications, such as toxicity, neutropenia, and bone marrow suppression during clinical trials, due to a lack of selectivity and specificity within the human kinome." (PMID 26557691, 2015). "Especially for the most relevant adverse effect of Plk1 inhibitors, the neutropenia can be attributed to the transient inhibition of bone marrow precursor cell proliferation." (PMID 36845678, 2023). "The safety outcomes of the Eg-5 inhibitors were similar to those of Mps1, Plk1, and Aurora kinase inhibitors, with neutropenia as the most common AE." (PMID 34371703, 2021). "Although a normal cell line was not included in the study for comparison, numerous studies, both in vivo and even clinical trials, have established that PLK1 inhibition by siRNA or BI 2536 is well tolerated, with neutropenia being the main side effect." (PMID 22309939, 2012). "Third, hematologic toxicities such as neutropenia and thrombocytopenia remain the most common dose-limiting adverse events of PLK1 inhibitors and may restrict their use in combination with other myelosuppressive agents, including platinum and paclitaxel." (PMID 41458961, 2025). "Specifically, it is tempting to postulate that BAL0891s unique profile could potentially alleviate the primary dose-limiting toxicity associated with PLK1-and TTK-specific inhibitors; namely hematologic toxicity (including neutropenia)." (PMID 39184047, 2024). "Most interestingly, nutlin-3 protects mice from PLK1 (polo-like kinase 1) inhibitor–induced neutropenia without abating the anticancer potency of the mitotic poison." (PMID 21512204, 2011). "In contrast, preclinical studies on genetically-engineered mice showed that specific Plk1 mRNA knockdown by short hairpin RNA did not result in typical hematological side effects, such as anemia or neutropenia, and did not affect spermatogenesis or cellular proliferation." (PMID 32060361, 2020).
renal cell carcinoma (9 papers, 2017 to 2026). "Overexpression of PLK1 promotes the proliferation of renal cell carcinoma (RCC) cells and inhibits apoptosis." (PMID 35581376, 2022). "For instance, phosphorylation of MCM3 by PLK1 was proved to participate in the proliferation and apoptosis of renal cell carcinoma cells." (PMID 33828075, 2021). "In renal cell carcinoma (RCC), we identified conserved metabolichighUBE2C+ cancer cells linked to poor outcomes, metabolic reprogramming and low differentiation, and PLK1+ NK cells, plasma cells, and CDC20+ macrophages associated with advanced stages and unfavorable prognosis." (PMID 42196432, 2026). "Gao showed that PLK1 affects cell proliferation and apoptosis by boosting MCM3 phosphorylation in renal cell carcinoma (RCC)." (PMID 34992654, 2021).
endometrial cancer (8 papers, 2012 to 2026). Primary or metastatic malignant neoplasm involving the endometrium (mucous membrane that lines the endometrial cavity). "Autocrine activation of JAK/STAT3 signal by OSM in ARID1A-deficient endometrial cancer cells promotes PLK1 levels, inducing mitotic abnormality." (PMID 41800254, 2026). "Polo-like kinase 1 (Plk1) is widely recognized as an oncogene that promotes cell proliferation by regulating cell division, DNA damage response, and genome stability and has been shown to be overexpressed in many cancers, including endometrial cancer." (PMID 40166466, 2025). "The other study reported higher transcript levels for baculoviral IAP repeat containing 7 (BIRC7), polo-like kinase 1 (PLK1) and multiple cell cycle regulatory proteins in endometrial cancer specimens from Black compared to White patients." (PMID 35887124, 2022).
head and neck squamous cell carcinoma (8 papers, 2012 to 2024). A squamous cell carcinoma that arises from any of the following anatomic sites: lip and oral cavity, nasal cavity, paranasal sinuses, pharynx, larynx, and salivary glands. "High PLK1 expression is associated with poor prognosis in head and neck squamous cell carcinoma." (PMID 31387297, 2019). "Polo-like kinase 1 (PLK1) is a critical therapeutic target in the treatment of head and neck squamous cell carcinoma (HNSCC)." (PMID 38536443, 2024). "However, in head-and-neck squamous cell carcinoma, PLK1 siRNA significantly increased the CCNB1 mRNA level." (PMID 29246203, 2017).
hepatoblastoma (8 papers, 2013 to 2025). Hepatoblastoma (HB) is a malignant hepatic tumor and is the most common pediatric liver cancer. "While the clinical utility of drugging these targets with selective inhibitors awaits future testing, a PLK1 inhibitor, Volasertib, has shown anticancer activity in high-risk hepatoblastoma models." (PMID 37414763, 2023). "Yamada and colleagues showed that PLK1 mRNA was significantly more abundant in hepatoblastomas compared to normal liver specimens and was associated with a significantly poorer 5 –year survival." (PMID 30969990, 2019). "Further studies could include the analysis of PLK1 expression/phosphorylation status in other high-risk hepatoblastoma histology cohorts to determine the possible benefit of volasertib treatment for other groups." (PMID 31741706, 2019). "PLK1 overexpression in hepatoblastoma has been previously characterized as a potential therapeutic target and here we show that PLK1 is also overexpressed in our sample set." (PMID 31741706, 2019). "To cross validate the overexpression of PLK1 in aggressive hepatoblastoma, we used the 16-gene classifier on another separate set of microarray data from 55 hepatoblastoma samples." (PMID 31741706, 2019). "To validate volasertib’s selectivity for hepatoblastoma cells over normal hepatocytes we investigated the expression of PLK1 in normal and hepatoblastoma tumor tissue by using publically available genomic databases." (PMID 31741706, 2019). "In addition, we examined the two other HSP90 client proteins involved in the cell cycle and hepatoblastoma, namely the polo-like kinase 1 (PLK1) and the aurora kinase A (AURKA)." (PMID 40282517, 2025). "Here, we further identify polo-like kinase 1 (PLK1) as a potential therapeutic target in hepatoblastoma that may have a favorable therapeutic index." (PMID 31741706, 2019). "We identified various classes of inhibitors targeting a wide range of hepatoblastoma organoids, including those that target HDAC, the proteasome, PLK-1, and FGFRs." (PMID 39567475, 2024). "Therefore, there is evidence that the PP2A environment may be dysregulated in poor prognosis hepatoblastoma, and FTY720 may have a significant impact on poor prognosis hepatoblastoma tumors through targeting both the Plk1 axis and the Wnt/beta-catenin pathway via effects on PP2A." (PMID 30969990, 2019). "Despite evidence of PLK1 over-expression, PLK1 inhibitors have not been pre-clinically or clinically tested for hepatoblastoma." (PMID 31741706, 2019). "PLK1 is overexpressed in hepatoblastoma biopsies relative to normal liver tissue." (PMID 31741706, 2019).
lung squamous cell carcinoma (8 papers, 2017 to 2026). "In conclusion, PLK1 expression is increased in lung squamous cell carcinoma tissues, and associated with malignant status and prognosis in lung squamous cell carcinoma patients." (PMID 28724602, 2017). "In conclusion, high expression of PLK1 is associated with the aggressive progression and poor prognosis in lung squamous cell carcinoma patients." (PMID 28724602, 2017). "Moreover, multivariate cox regression analysis, after adjusting for clinicopathological factors confirmed that high PLK1 expression at the protein level was independently associated with poor outcome in patients with lung squamous cell carcinoma." (PMID 33922264, 2021). "In lung squamous cell carcinoma, PLK1/3/4 promoters presented a higher methylation in primary tumour, whereas PLK2 promoter methylation was at lower level in primary tumour than that in normal sample." (PMID 34080290, 2021). "The methylation of PLK1/3/4 genes kept a higher level in lung squamous cell carcinoma sample than that in normal lung sample; however, PLK2 methylation stayed at lower level in lung squamous cell carcinoma than normal tissue." (PMID 34080290, 2021). "While in lung squamous cell carcinoma, the methylation was strengthened in PLK1/3/4 genes while weakened in PLK2 gene." (PMID 34080290, 2021). "Plk1 expression leads to poor prognosis in lung, bladder, and kidney clear cell carcinomas patients, whereas in patients suffering from thymoma, lung squamous cell carcinoma or rectum adenocarcinoma, Plk1 higher levels seem to indicate a much better prognosis." (PMID 30862113, 2019). "The prognostic value of PLK1 protein expression in lung squamous cell carcinoma patients was also explored in 132 lung squamous cell carcinoma tissue specimens through immunohistochemistry." (PMID 28724602, 2017). "PLK1 mRNA and protein expressions were detected in lung squamous cell carcinoma and normal lung tissues by using quantitative real-time PCR (qRT-PCR) and immunohistochemistry." (PMID 28724602, 2017). "Kaplan–Meier survival analysis showed lung squamous cell carcinoma patients, that expressed high level of PLK1 protein, had lower overall survival compared with patients with low level of PLK1 protein expression (P<0.001)." (PMID 28724602, 2017). "The aim of our study is to present more evidence about the clinical and prognostic value of PLK1 in lung squamous cell carcinoma patients." (PMID 28724602, 2017). "The univariate and multivariate analyses showed PLK1 protein high expression was an unfavorable prognostic biomarker for lung squamous cell carcinoma patients." (PMID 28724602, 2017). "Compared with paired adjacent normal lung tissues, the PLK1 expression was increased in lung squamous cell carcinoma tissues." (PMID 28724602, 2017). "The clinical significance of PLK1 protein expression in lung squamous cell carcinoma patients was explored in 132 lung squamous cell carcinoma tissue specimens through immunohistochemistry." (PMID 28724602, 2017). "We further confirmed the status of PLK1 mRNA and protein expressions in lung squamous cell carcinoma tissue samples." (PMID 28724602, 2017). "The aim of our study was to explore the clinical and prognostic significance of PLK1 in lung squamous cell carcinoma patients." (PMID 28724602, 2017). "Compared with paired adjacent normal lung tissues, the levels of PLK1 mRNA was overexpressed in lung squamous cell carcinoma tissues with an average increase of 3.85-fold (P<0.001)." (PMID 28724602, 2017). "We observed that PLK1 protein expression was increased in lung squamous cell carcinoma tissues in 54.5% (72/132) compared with adjacent normal tissues in 21.2% (7/33) (P=0.001)." (PMID 28724602, 2017). "Finally, CDK1, PLK1, PCNA, ZWINT and NDC80 identified as hub genes for underlying molecular mechanisms of lung squamous cell carcinoma lymphatic metastasis." (PMID 37185598, 2023).
lung squamous cell carcinoma (continued). "Finally, CDK1, PLK1, PCNA, ZWINT and NDC80 identified as hub genes for underlying molecular mechanisms of lung squamous cell carcinoma and lymphatic metastasis." (PMID 37185598, 2023). "PLK1 is an independent unfavorable prognostic factor for lung squamous cell carcinoma patients." (PMID 28724602, 2017). "Furthermore, PLK1 protein expressions in 132 lung squamous cell carcinoma tissues and 33 adjacent normal lung tissues were detected by immunohistochemical staining." (PMID 28724602, 2017). "Thus, we supposed that PLK1 may serve as an important biomarker for lung squamous cell carcinoma patients." (PMID 28724602, 2017).
multiple myeloma (8 papers, 2011 to 2021). "The organotellurate immunomodulator AS101 induces G2/M arrest in myeloma cells and downregulates Cdc25C, Plk-1 (a serine/threonine kinase), and Ilk-1 (essential for regulating the activity of Akt) in mouse 5T33 myeloma cells." (PMID 31772702, 2019). "Preclinical research identified several components of mitosis as possible interesting targets in myeloma treatment, including kinesin motor protein Eg5, aurora A kinase and Plk1, which are all involved in the spindle formation." (PMID 29163849, 2017). "The Plk1 inhibitor BI2536 has proven to possess potent anti-myeloma activity." (PMID 29163849, 2017). "In myeloma, Plk1 is increased and may induce chromosome missegregation." (PMID 29163849, 2017). "As described in this review, inhibitors of half of these (PLK1, TYK2 and AURKB) have been studied to one degree or another as potential targets in MM while the other three represent fertile ground for new anti-myeloma development." (PMID 27655636, 2016). "Together, PLK2 expression, but not PLK1, was regulated by IRE1α, and its pharmacological inhibition induced apoptosis, demonstrating the cell-cycle arrest in human myeloma cells." (PMID 32878237, 2020). "Of note, Plk1 is not cleaved following treatment with other pro-apoptotic agents including staurosporine or Imatinib in K562 cells or Velcade in the U266 multiple myeloma cell line." (PMID 29541386, 2018).
retinoblastoma (8 papers, 2013 to 2025). A malignant tumor that originates in the nuclear layer of the retina. "A previous study found that xanthatin exerted its pharmacological effects by inhibiting the PLK1-mediated G2/M pathway and inducing retinoblastoma cell apoptosis." (PMID 40309730, 2025). "Accordingly, the MYC-target gene PLK1 was one of the top upregulated genes in RB1ko, which fits the anti-proliferative effect of PLK1-inhibition in retinoblastoma cell lines." (PMID 35565295, 2022). "The Retinoblastoma RB factor is one of the many factors, which control the expression of PLK1." (PMID 26799423, 2016). "However, other molecular attributes of AVPCa, in particular overexpression of c-Myc, Aurora A, N-Myc, and PLK1 and loss of retinoblastoma expression were not evident in IGR-CaP1 cells." (PMID 28103576, 2017). "Interestingly, it has been found that PLK1 expression is upregulated in the case of Retinoblastoma tumor suppressor (RB) inactivation, suggesting that PLK1 may be also a target of the RB pathway." (PMID 24025726, 2013). "Collectively, these findings highlight a distinct therapeutic sensitivity profile of MYCN-overexpressing retinoblastoma cells, particularly to transcriptional inhibitors (THZ1, Flavopiridol) and the PLK1 inhibitor Volasertib." (PMID 40943594, 2025).